MDM2 (MDM2 proto-oncogene)
Diseases named in the same sentence as MDM2 in open-access papers (continued):
Sharing a sentence is not in itself a finding about the gene and the disease.
tumor (continued). "The mechanistic explanation of MDM2-induced tumor chemoresistance was confirmed by MDM2 depletion with siRNA that was sufficient to rescue ADR-induced p53Ser46 phosphorylation and PARP cleavage inhibited by cobalt." (PMID 19714248, 2009). "In 2006, along the analysis of MDM2 alternative transcripts induced by UV irradiation in some human tumor cell lines, Lozano’s group found out two alternative transcripts of MDM4, called XALT1 and XALT2." (PMID 19721810, 2009). "Some tumor-derived cells are partially insensitive to the mdm2-mediated cell cycle inhibition and mdm2 can be stably overexpressed in these tumor cells." (PMID 19445705, 2009). "As expected from the previously published analyses of these populations, the MDM2 SNP309 locus affects the age of tumor diagnosis in a significant manner as demonstrated by a significant level of mutual information (0.10 bits, p = 0.007, Permutation Test)." (PMID 18398474, 2008). "The information-theoretic approach allowed for the probing of statistical dependencies among all three variables (the alleles of MDM2 SNP309, gender and the age of first tumor onset)." (PMID 18398474, 2008). "We observed that adoptive transfer of MDM2-specific effector CTL into tumor-bearing resulted in the induction of T cell unresponsiveness." (PMID 17406677, 2007).
tumor (continued). "Recently, novel boronic–chalcone derivatives have been described as putative MDM2 antagonists with antitumour effect against cultured tumour cells." (PMID 15452548, 2004). "The overall frequency of MDM2 amplification in human tumour tissue samples is approximately 7% with the highest frequency observed in soft-tissue sarcomas (20–30%), osteosarcomas (16%) and oesophageal carcinomas (13%)." (PMID 15452548, 2004). "The mdm2 gene was found to be upregulated in human tumours and tumour cell lines by gene amplification, increased transcript levels and enhanced translation." (PMID 15452548, 2004). "These tumours were also examined for MDM2 and P63 amplification, and for expression of p16INK4a/CDKN2a, cyclin E, p27Kipland Cox2." (PMID 11531258, 2001). "Expression of mdm2 was seen in 14% of the primary tumours, of which four cases were marked positive." (PMID 10389975, 1999). "Whereas 20q13 showed a very strong correlation to CCND1 amplification, that of MDM2 was prevalent in MYC-amplified tumours." (PMID 8980401, 1996). "Immunohistochemical analysis of the formalin-fixed, paraffin-embedded tumours demonstrated that 7/97 (7%) had nuclear expression for MDM2 in 10-50% of the tumour cells (type 2 staining) and were denoted MDM2+." (PMID 7734324, 1995). "Southern analysis of tumour DNA revealed that 2/29 tumours demonstrated amplification of the MDM2 gene." (PMID 8198970, 1994).
tumor (continued). "In vivo, MDM2 deficiency increased tumor cell necroptosis, promoted inflammatory remodeling of the tumor microenvironment (TME), and enhanced CD8+ T cell infiltration, leading to improved tumor control." (PMID 42095082, 2026). "Furthermore, in patients with NSCLC who received platinum-based chemotherapy, the level of MDM2 expression in the tumour correlated with poor progression-free survival, which further validates the key role of MDM2 in response to platinum compounds." (PMID 41545766, 2026). "This suggests that PAK6-mediated regulation of MDM2 may exert both oncogenic and tumor-suppressive effects depending on the cancer context." (PMID 40650306, 2025). "However, a PROTAC-induced increase of mdm2 both in CDK4/6i sensitive and resistant MCF-7 cell is associated with a strong anti-tumor effect." (PMID 40452017, 2025). "This amplification of MDM2, combined with the other histological and immunohistochemical findings, conclusively established the diagnosis of DDLPS with IMT-like features, underscoring the tumor’s aggressive biological behavior and diagnostic complexity." (PMID 40211332, 2025). "Some studies also suggest that MDM2 has pro-angiogenic effects that may contribute to tumor development." (PMID 41303785, 2025). "In particular, the proliferative goals of MDM2 comprise the activation of E2 F1 transcriptional action amplified E2 F1 protein stability, breakdown of the Rb-E2 F1 complex, and suppressing inhibitory effects of Rb on tumor." (PMID 40580306, 2025).
tumor (continued). "The data demonstrated that MDM2 expression is enriched in tumor cells compared to normal tissues, which may enhance the specificity of this PROTAC." (PMID 40113745, 2025). "The recommendation for the administration of Docetaxel could be withdrawn for patients with MDM2-amplified tumors since the tumor cells developed a therapy resistance mechanism against Docetaxel." (PMID 41299419, 2025). "Future research is necessary to identify other factors regulating MDM2 regulation in RCC, assess the prognostic value of rs2270744 in RCC patients, and perform high-throughput sequencing in tumor DNA/RNA to discover mutations and gene expression alterations related to RCC progression and survival." (PMID 39857959, 2025). "Additionally, MDM2 ́s potential as a therapeutic target is being evaluated in various tumor entities." (PMID 41299419, 2025). "MDM2’s interaction with Nbs1 impairs homologous recombination, increasing genomic instability, interfering with DNA repair, and promoting aberrant chromosomal events that facilitate neoplastic transformation and tumour progression." (PMID 41515979, 2025). "MDM2 expression was reported to lead to a higher resistance to T cell-mediated tumor killing." (PMID 41299419, 2025). "Furthermore, NFATc1 upregulates MDM2, which not only enhances metabolic reprogramming but also facilitates cell cycle progression, thereby further promoting tumor proliferation." (PMID 41203626, 2025). "Moreover, in numerous tumors, downregulation of MDM2 has been shown to suppress tumor growth or induce apoptosis." (PMID 40487391, 2025). "In this study, 656 tumor samples were screened for MDM2 amplification." (PMID 41299419, 2025). "Notably, the expression of Mdm2, a potent tumor oncogene, significantly increased in tissues with MCPIP1 mutations." (PMID 39815326, 2025). "Some IS tumor cells expressed MDM2 (8/11, 72.7%), SMA (3/11, 27.3%), and CD34 (2/11,18.2%)." (PMID 41246336, 2025).